HNF1A-AS1 (HNF1A antisense RNA 1)
Synonyms: FLJ38690; HAS1; HASTER; C12orf27; NCRNA00262
Gene: Long non-coding RNA gene on chromosome 12 (120,941,723 to 120,980,968, reverse strand). Ensembl gene ENSG00000241388.
Diseases named in the same sentence as HNF1A-AS1 in open-access papers:
HNF1A-AS1 is named in the same sentence as 9 diseases in open-access papers, as found by Europe PMC text mining. Sharing a sentence is not in itself a finding about the gene and the disease. The quoted sentences say what the papers report.
asthma (1 paper, 2020). "My findings have linked both of FAM105A and HNF1A Antisense RNA 1 (HNF1A-AS1) to moderate-to-severe and severe asthma." (PMID 32512817, 2020).
hepatocellular carcinoma (1 paper, 2019). A malignant tumor that arises from hepatocytes. "Expressions of the autophagy-inducing lncRNAs, including HNF1A antisense RNA 1 (Hnf1a-as1), HOX transcript antisense RNA (Hotair), and hepatocellular carcinoma up-regulated long non-coding RNA (Hulc), were up-regulated in HCC." (PMID 31614437, 2019).
osteosarcoma (1 paper, 2021). A usually aggressive malignant bone-forming mesenchymal neoplasm, predominantly affecting adolescents and young adults. "The expression levels of HNF1AAS1 were significantly higher in osteosarcoma-derived tissue compared with adjacent non-tumor tissues, and it is associated with a poor prognosis in osteosarcoma patients." (PMID 34577571, 2021). "It was suggested that HNF1AAS1 might act as an oncogenic lncRNA that boosts proliferation and metastasis in osteosarcoma cell lines and activates the Wnt/β-catenin signaling pathway." (PMID 34577571, 2021).
rhabdomyosarcoma (1 paper, 2022). A rare aggressive malignant mesenchymal neoplasm arising from skeletal muscle. "The remaining four DElncRNAs (MEG3, maternally expressed gene 3; RMST, rhabdomyosarcoma 2-associated transcript; HNF1A-AS1, HNF1A antisense RNA 1; and PVT1, and plasmacytoma variant translocation 1) and two DEmiRNAs (hsa-mir-429 and hsa-mir-200a) appeared to be protective." (PMID 36101743, 2022).
cancer (2 papers, 2017 to 2020). A tumor composed of atypical neoplastic, often pleomorphic cells that invade other tissues. "Among the cancer-related lncRNAs, lncRNA HNF1A antisense RNA 1 (HNF1A-AS1) has been reported to be highly expressed and act as an oncogene in various human malignancies." (PMID 33024199, 2020). "HNF1A-AS1 (HNF1A antisense RNA 1, C12 or f27) is a novel long non-coding RNA that acts as a potential biomarker and is involved in development and progression of several cancers." (PMID 29100339, 2017).
HNF1A-AS1 also shares sentences with these, for which no sentence is quoted: diabetes mellitus (2 papers); esophageal squamous cell carcinoma (1); liver disease (1); lung adenocarcinoma (1).